RN7SKP37 (RN7SK pseudogene 37)
Gene: Miscellaneous RNA gene on chromosome 10 (21,933,143 to 21,933,438, forward strand). Ensembl gene ENSG00000201364.
Homologues: Orthologues: chimpanzee 7SK (99% identical). Paralogues in human: 7SK (83% identical), RN7SKP180 (80% identical), RN7SKP255 (80% identical), RN7SKP9 (80% identical), RN7SKP124 (79% identical), RN7SKP204 (79% identical), RN7SKP243 (79% identical), RN7SKP79 (79% identical), RN7SKP176 (79% identical), RN7SKP189 (79% identical), RN7SKP118 (78% identical), RN7SKP28 (78% identical), and 284 more.